HSPA5 (heat shock protein family A (Hsp70) member 5)
Diseases named in the same sentence as HSPA5 in open-access papers (continued):
Sharing a sentence is not in itself a finding about the gene and the disease.
lung carcinoma (111 papers, 2008 to 2026). "In contrast, research on the mouse lung cancer model appears, where it has been shown that overexpression of this protein is associated with poor forecasts in therapy, and HSPA5 inhibition by HA15 promoted the apoptosis of tumour cells." (PMID 37377864, 2023). "The downregulation of SIRT1/2 can induce protective autophagy in lung cancer by increasing the acetylation of HSPA5, which in turn elevates ATF4 and DDIT4 levels, suppressing mTOR and promoting pro-survival autophagy." (PMID 39403142, 2024). "In lung cancer, reports indicate decreased HSPA5 expression with Aftanib by measuring the level of HSPA5 mRNA before and after treatment." (PMID 37377864, 2023). "This compound increases DDIT3 expression at the gene and protein levels and induces both HSPA5 mRNA and HSPA5 protein in lung cancer 95-D and A549 cells." (PMID 36497321, 2022). "BDMC increases ER stress-associated proteins expression such as HSPA5, DDIT3, ERN1, ERN2/IRE-1β, ATF6, ATF6B and CASP4, which results in cell apoptosis in the human lung cancer NCI H460 cell line." (PMID 36497321, 2022). "The anti-cancer activity of DMC occurs through promoted expression of ER stress-associated proteins HSPA5, DDIT3, ERN1, ATF6A, ATF6B, CASP4 and CAPS12 in human lung cancer NCI-H460 cells." (PMID 36497321, 2022). "In conclusion, we found that EIF2AK3-rs6750998 was a protective variant against the risk of lung cancer, while EIF2AK3-rs867529, HSPA5-rs391957, and DDIT3-rs697221 were all susceptible variants for the disease." (PMID 35923704, 2022). "Accordingly, lower levels of ITGA2B and increased levels of the ER proteins P4HB, CALR and HSPA5 in patients with lung cancer and LA suggest some common affected pathways in their prothrombotic pathology." (PMID 34066760, 2021). "More importantly, HSPA5 mRNA levels increase 54.4 fold than that of ACE2 in normal lung, and 253 fold in lung cancer, indicating that HSPA5 should play important roles for SARS-Cov-2 entry in cancer patients through the lungs." (PMID 33767597, 2021). "In the current study, FVIII was also significantly increased in the plasma of patients with lung cancer and showed a predominant correlation with the ER proteins HSPA5 and CALR in comparison to all other proteomic investigated platelet proteins." (PMID 34066760, 2021). "HSPA5 mRNA levels increase 253-fold than that of ACE2 in lung cancer, indicating that HSPA5 migh play more important roles for SARS-Cov-2 entry in cancer patients through the lungs." (PMID 33767597, 2021). "Elevated levels of ER chaperones P4HB, CALR and HSPA5 indicated the induction of the ER unfolded protein response (UPR) in platelets of patients with lung cancer." (PMID 34066760, 2021). "Ectopic expression of SCARA5 suppressed proliferation of lung cancer both in vitro and in vivo through upregulation of HSPA5 expression, which inhibited FOXM1 expression resulting in G2/M arrest of the A549 cell line." (PMID 34150631, 2021). "For instance, we identified three heat shock protein (HSP) genes, HSP 90 alpha family class B member 1 (HSP90AB1), HSP family A member 8 (HSPA8), and HSP family A member 5 (HSPA5), as novel biomarkers in lung cancer and GBM." (PMID 33277589, 2020). "It is worth noting that, among these identified proteins, five proteins (Hsp90, ENO1, ALDOA, PDIA6, HSPA5) were reported as the differential proteins identified in lung cancer tissues as compared to normal lung in our previous work." (PMID 27684953, 2016). "Also, in glioblastoma, lung cancers, and pancreatic cancer, radiation-induced cs-HSPA5 upregulation has been recorded." (PMID 41301006, 2025). "Moreover, in the normal lungs, the mRNA level for HSPA5 was a 54.4-fold increase than that of ACE2, and in lung cancer, it was a 253-fold increase, implying that HSPA5 plays a vital role in SARS-CoV-2 invasion in cancer progression by the lungs." (PMID 37275848, 2023). "LETM1/HSPA5 axis or HSPA5-LETM1 interaction was revealed to play roles in lung cancer progression." (PMID 37275848, 2023).
lung carcinoma (continued). "However, little information is found about the single-nucleotide polymorphisms (SNPs) in EIF2AK3/PERK, HSPA5/GRP78, and DDIT3/CHOP in cancer patients, especially those with lung cancer." (PMID 35923704, 2022). "HSPA5 is also overexpressed in some cancers, including breast, hepatocellular, and lung cancer." (PMID 29164150, 2017). "Evidence of HSPA5 promoted the EMT process together with previous results, it would be important to note that DAL-1 might inhibit HSPA5 then impact on EMT in lung cancer." (PMID 25609022, 2015). "Furthermore, inhibition of HSPA5 by HA15 induced apoptosis in lung cancer cells." (PMID 37807968, 2023). "Separate analysis of patients with gastric cancer and non–small cell lung cancer showed that all 4 of the analytes (CLGN, TXD15, HSPA5, and RCN1) were significantly increased in patients who developed clots in both gastric and non–small cell cancer cohorts." (PMID 37651191, 2023). "For pathophysiological explorations of platelet proteome changes in patients with lung cancer we concentrated on four candidates described to be involved in the processing of coagulation proteins, which are F13A1 and the ER proteins P4HB, CALR and HSPA5." (PMID 34066760, 2021). "This induction of the UPR and correlations of FVIII with P4HB, HSPA5 and CALR levels may also take place systemically in patients with lung cancer." (PMID 34066760, 2021). "In addition, HSPA5 expressions in lung cancers were upregulated compared to normal tissues from TCGA dataset (Data not shown)." (PMID 33767597, 2021). "However, there is no reported role for HSPA5 in lung cancer at present, while Hsp90 has been regarded as serum biomarker and therapeutic target in lung cancer." (PMID 27684953, 2016). "In order to test which genes changes more in lung cancer, we analyzed HSPA5 mRNA and ACE2 mRNA in TCGA dataset from 994 samples and found that HSPA5 mRNA levels was 253-fold than that of ACE2, indicating that HSPA5 might play important roles for SARS-Cov-2 entry in cancer patients through lungs." (PMID 33767597, 2021).
prostate carcinoma (107 papers, 2010 to 2025). A carcinoma that arises from epithelial cells of the prostate gland. "Genes associated with ETV4-fusion-positive prostate cancers were used as the input, and four therapeutic candidate targets, PARP1, NQO1, HSPA5, and TOP1, and the respective selective drugs, olaparib, amrubicin, fluorouracil, and irinotecan, were identified." (PMID 36289913, 2022). "In particular, HSPA5 was upregulated in 40% (6/15) and in 66% (2/3) of the clinical studies available for prostate carcinoma and MM tissues, respectively." (PMID 30563499, 2018). "Antibodies against HSPD1, HSPA5 and ATP5B were added to the panel as they had been previously identified specifically in LEVs compared to exosomes, in addition to being associated with prostate cancer progression." (PMID 33801459, 2021). "Notably, a recent ubiquitinome-wide analysis identified the heat shock 70 kDa protein 5 (HSPA5, also known as BiP or GRP78) as a target of USP22-mediated deubiquitination in prostate cancer cells." (PMID 34007022, 2021). "Indeed, conditional knockout of the ER chaperone GRP78 (HSPA5) in the prostate of mice with PTEN inactivation suppressed prostate cancer growth." (PMID 33218188, 2020). "Changes in expression of genes in this pathway, including HSPA5 as a marker of activation of this pathway, are related to a variety of cancers including breast, gastric, lung, colon and prostate cancers characterized by high pathologic levels, tumor recurrence, and low survival." (PMID 31249762, 2019). "PARP1, NQO1, HSPA5, and TOP1 were identified as potential molecular targets for ETV4-fusion-positive prostate cancer, and olaparib, amrubicin, fluorouracil, and irinotecan were suggested as candidate drugs, respectively." (PMID 36289913, 2022). "GRP78 (BIP, HSPA5) is a member of the HSP70 family and cell-surface-located GRP78 is found in a variety of malignant tumours including breast, lung, gastric, hepatocellular and prostate cancers." (PMID 23667612, 2013).
glioma (92 papers, 2010 to 2026). A benign or malignant brain and spinal cord tumor that arises from glial cells (astrocytes, oligodendrocytes, ependymal cells). "Although HSPA5 is a recognized marker of poor prognosis in glioma, its underlying mechanistic function remains poorly defined." (PMID 41654508, 2026). "Mechanistically, DHA caused endoplasmic reticulum (ER) stress in glioma cells, which resulted in the induction of HSPA5 expression by protein kinase R-like ER kinase (PERK)-upregulated activating transcription factor 4 (ATF4)." (PMID 31519193, 2019). "The network topology analysis performed in this study revealed a set of central nodes associated to glioma malignancy, such as Map3k14, Mapk1, Actn4, Hspa5, Atf2, Rac1,E2f1, Shc1, Pik3ca, Akt1, Vim and Egr1." (PMID 26582089, 2015). "Previous studies have demonstrated that EP300‐mediated HSPA5 acetylation at K353 enhances resistance in pancreatic cancer cells, whereas dihydroartemisinin‐induced ERS mitigates iron death in glioma cells through the PERK/ATF 4/HSPA5 pathway." (PMID 40371728, 2025). "Accordingly, HSPA5 downregulation or silencing increased the sensitivity of glioma cells to various chemotherapeutic agents, such as TMZ, 5-fluorouracil, irinotecan, etoposide, and cisplatin." (PMID 41002413, 2025). "Other preclinical studies have investigated the ability of HSPA5 inhibitors, antibodies, and other agents that bind to and inhibit HSPA5 to reduce glioma cells’ viability and enhance the sensitivity to chemo-radiotherapy." (PMID 41002413, 2025). "HSP70 protein 5 [HSPA5, also known as glucose‐regulating protein 78 (GRP78)] is highly expressed in many malignant cancers, including gliomas in the central nervous system." (PMID 38494858, 2024). "The study also highlighted the inhibitory effect of borax‐induced ferroptosis on cell proliferation in glioma cells, achieved through the modulation of the HSPA5/NRF2/GPx4/GSH regulatory pathways." (PMID 38494858, 2024). "The upregulation of HSPA5 in brain tumours, especially gliomas, has been observed, and its involvement in promoting glioma proliferation, evading apoptosis and facilitating metastatic movement has been identified." (PMID 38494858, 2024). "Among the identified proteins, HSPA5 (BiP) was the most abundant chaperone, and BiP has been reported to play crucial roles in glioma." (PMID 39281835, 2024). "VAP peptides, exhibiting high binding affinity in vitro to HSPA5 overexpressed on glioma, was a flexible and multifunctional peptide to mediate glioma targeting." (PMID 37385987, 2023). "We transfected HSPA5 siRNA into LIMD1-AS1-overexpressed SF126 glioma cells and found that knockdown of HSPA5 expression significantly reduced LIMD1-AS1-induced increase IFN signatures mRNA levels in SF126 glioma cells." (PMID 37385987, 2023). "We found that LIMD1-AS1 knockdown markedly reduced the HSPA5 protein level in the LN-18 and T98G glioma cells." (PMID 37385987, 2023). "Among these identified proteins, we selected HSPA5 protein base on HSPA5 correlated with LIMD1-AS1, highly expressed in glioma, and associated with overall survival and disease-free survival in glioma patients." (PMID 37385987, 2023). "This is because DHA causes endoplasmic reticulum stress in glioma cells, which up regulates the expression of activated transcription factor 4 (ATF4) and induces the expression of HSPA5 by activating protein kinase R-like endoplasmic reticulum kinase (PERK)." (PMID 35478955, 2022). "Dihydroartemisinin (DHA) can activate ATF4 by promoting the level of p-ERK in glioma cells, thereby increasing the level of heat shock protein family A (Hsp70) member five HSPA5." (PMID 35784729, 2022). "Western blotting showed HSPA5 protein level in WHO II glioma tissue and WHO III/IV glioma tissue were both elevated obviously compared with normal brain tissue." (PMID 34026352, 2021). "It was reported that this gene is over-expressed in many types of cancers however the high expression of HSPA5 in glioma was seldom reported." (PMID 34026352, 2021).
glioma (continued). "Excluding the previously reported prognostic markers of gliomas from this study, the expression of HSPA5 and MTPN were examined by qRT-PCR and immunohistochemical assay." (PMID 34026352, 2021). "The results of the study showed that the gene expression level of HSPA5 increased with the grades of gliomas." (PMID 34026352, 2021). "By literature search, we excluded the previously reported prognostic biomarkers of gliomas, and obtained two gene signatures (HSPA5 and MTPN) that can predict the prognosis of both white and Asian populations." (PMID 34026352, 2021). "Immunohistochemical results indicated that compared with normal brain tissue, the positive expression of HSPA5 protein in gliomas rose obviously." (PMID 34026352, 2021). "We next restored GPX4 activity in glioma cells using an HA-tagged GPX4 expression vector in HSPA5-silenced glioma cells." (PMID 31519193, 2019). "Given that GPX4 is the critical enzyme that reduces lipid peroxidation to prevent ferroptosis, we thus assessed the roles of GPX4 in HSPA5-mediated ferroptotic resistance against DHA in glioma cells." (PMID 31519193, 2019). "Like erastin, DHA also induced ER stress in a dose-dependent manner in glioma cells, as indicated by gradually elevated expression of HSPA5 and CHOP proteins." (PMID 31519193, 2019). "Targets HSPA5 to resensitize glioma cells to temozolomide treatment." (PMID 41301006, 2025). "Inspired by the boron neutron capture therapy, a new form of cancer therapy that is currently being researched using boron-containing agents and ionizing radiation, borax (sodium borate) induced ferroptosis in glioma cells in vitro by inhibiting the HSPA5/NRF2/GPX4/GSH signaling pathways." (PMID 39062119, 2024). "Furthermore, HSPA5 has been reported to maintain the stability of GPx4, a critical enzyme involved in lipid peroxidation and protection against ferroptosis, in glioma cells." (PMID 38494858, 2024). "Therefore, our results suggest that LIMD1-AS1 promotes the malignant phenotype of glioma cells by directly binding the HSPA5 protein and enhancing its stability." (PMID 37385987, 2023). "Moreover, an IF and RNA-FISH assay results showed that LIMD1-AS and HSPA5 were predominantly colocalized in the cytoplasm of LN-18 and T98G glioma cells." (PMID 37385987, 2023). "Finally, LIMD1-AS1 directly interacts with HSPA5 and further specifies the transcriptional activation pattern on interferon signaling in glioma." (PMID 37385987, 2023). "In summary, our results provide novel evidence that epigenetic modifications of LIMD1-AS1 are mediated by CDK7-activated interferon pathways by directly binding HSPA5, which might contribute to glioma progression." (PMID 37385987, 2023). "Additionally, the level of p38 MAPK and Akt phosphorylation was higher after P2X7 activation, similarly to the total protein level of chaperones HSPA1 and HSPA5, and glioma stem cell marker CD133." (PMID 34964926, 2022). "In addition, activation of PERK/ATF4/HSPA5 pathway attenuated dihydroartemisinin-induced ferroptosis in glioma cells." (PMID 36591279, 2022). "It was reported that gga-miR-30c-5p inhibited glioma proliferation and invasion via targeting Bcl-2 and regulated cisplatin-induced apoptosis of renal tubular epithelial cells via targeting Bnip3L and Hspa5." (PMID 35632731, 2022). "The chaperone HSPA5 is involved in ferroptosis and contributes to an iron‐dependent non‐apoptotic cell death that stabilizes GPx4 and indirectly attenuates lipid peroxidation in glioma cells; therefore, we excluded HSPA5 from further study." (PMID 35984750, 2022). "Collectively, these data suggested that ferroptosis might be a novel anticancer mechanism of DHA in glioma and HSPA5 may serve as a negative regulator of DHA-induced ferroptosis." (PMID 31519193, 2019). "Furthermore, inhibition of PERK, ATF4 or HSPA5 enhanced cytotoxic effects of DHA on glioma cells both in vivo and in vitro." (PMID 31519193, 2019).